DKK2 (dickkopf Wnt signaling pathway inhibitor 2)
Diseases named in the same sentence as DKK2 in open-access papers (continued):
Sharing a sentence is not in itself a finding about the gene and the disease.
lung carcinoma (7 papers, 2017 to 2023). "A combination of all the 3 genotypic variants of DKK2 confers a four-fold increase in lung cancer risk." (PMID 34272429, 2021). "In the present study, we applied anti-DKK2 antibody to lung cancer mouse models driven by APC mutation." (PMID 31372243, 2019). "We also found significant upregulation of Dkk2 expression in human lung cancer tissues with APC mutations." (PMID 31372243, 2019). "Our study provided strong evidence supporting APC mutations-directed applications of anti-DKK2 targeted therapy in a wide range of cancer types, including lung cancer." (PMID 31372243, 2019). "We found significant upregulation of Dkk2 expression in APC-mutated lung cancers." (PMID 31372243, 2019). "Another recent study confirmed that DKK4: rs2073664 along with three polymorphisms (rs447372, rs419558, and rs17037102) of DKK2 within the Wnt signaling pathway could jointly predict the survival of lung cancer patients who were treated with platinum-based doublet chemotherapy." (PMID 32453708, 2020). "Administration of DKK2 antibody inhibited cancer growth via modulating tumor immune microenvironment in lung cancer mouse models." (PMID 31372243, 2019). "To investigate the role of DKK2 in lung cancer progression, we generated Dkk2 knockdown stable cell lines." (PMID 31372243, 2019). "We uncovered that increased DKK2 promoted lung cancer progression by modulating tumor immune microenvironment." (PMID 31372243, 2019). "Real-time PCR showed that Dkk2 expression was significantly upregulated in mouse lung cancer compared with normal lung tissue." (PMID 31372243, 2019). "Our studies indicated that DKK2 plays similar roles in both colorectal and lung cancer when they carry APC mutants." (PMID 31372243, 2019). "Concordantly, in situ hybridization confirmed that Dkk2 expression is present in lung cancer tissues." (PMID 31372243, 2019). "Significant upregulation of DKK2 expression was found in APC (adenomatous polyposis coli)-mutated non-SCLC lung cancers." (PMID 35101137, 2022). "We have evaluated the method by measuring the binding of the Wnt signaling inhibitors human Dickkopf1 (DKK1) and Dickkopf2 (DKK2) to the Wnt co-receptor lipoprotein-receptor related protein 6 (LRP6) in human lung cancer (NCI-H1703) and human embryonic kidney (HEK293T) cells." (PMID 32441251, 2020). "BaP induced significant hypermethylation of the DKK2 and EN1 gene promoter elements, and then inhibited DKK2 and EN1 gene expression, which promoted lung cancer cell proliferation and cancer development." (PMID 37391844, 2023). "Additionally, DKK2 and EN1 up-regulation inhibited cell proliferation in lung cancer cells." (PMID 27901495, 2017).
renal carcinoma (7 papers, 2012 to 2025). A carcinoma arising from the epithelium of the renal parenchyma or the renal pelvis. "A small case-control study (210 renal patients vs. 200 controls) reported GA/AA genotype of rs3206824 in DKK3 and GG genotype of rs17037102 in DKK2 were related with decreased risk of renal cancer and cancer deaths, respectively, in Japanese population." (PMID 27457487, 2016). "The DKK3 polymorphisms were associated with renal cancer and that the DKK2 rs17037102 polymorphism might be a predictor for survival in patients with renal cancer after radical nephrectomy." (PMID 26537097, 2015). "In renal cancer cells, the selective estrogen receptor modulator genistein reportedly abolished miR-1260b, which is able to suppress Wnt signaling modulators like Dkk2, and therefore preserved levels of these proteins." (PMID 33679613, 2021). "Dkk2 plays a key role in various human tissues and Dkk2 expression is known to be disrupted in multiple cancers including renal cancer, skin cancer, and different gastrointestinal cancers." (PMID 25826080, 2016).
colon cancer (6 papers, 2013 to 2024). "Taken together, DKK2-driven loss of HNF4α1 protein enhances Sox9 expression in colon cancer cells to generate LYZ+ cells with Paneth cell properties." (PMID 38659853, 2024). "Bulk RNA-seq analysis of DKK2-deficient colon cancer organoids showed reduction of the marker genes of Paneth cells, which play a role in the stem cell niche development." (PMID 38659853, 2024). "Mechanistically, DKK2 protein deficiency recovered protein levels of Hepatocyte Nuclear Factor 4 alpha (HNF4A) in colon cancer cells." (PMID 38659853, 2024). "DKK2 deficiency resulted in reduced glycolysis in mouse liver metastasized colon cancer cells." (PMID 38659853, 2024). "Notably, DKK2 induces the loss of HNF4α1 isoform in colon cancer cells followed by elevation of Sox9 expression lead to the formation of LYZ+ cancer cells exhibiting Paneth cell properties." (PMID 38659853, 2024). "Taken together, DKK2-mediated reduction of HNF4A protein promotes the generation of lysozyme positive cancer cells with Paneth cell properties in the metastasized colon cancers." (PMID 38659853, 2024). "We have recently reported that DKK2 enhanced Lgr5 expression in colon cancers through activation of c-Src." (PMID 38659853, 2024). "DKK2 is indispensable for the generation of cancer cells with Paneth cell properties in colon cancer organoids." (PMID 39535280, 2024). "Here we showed that DKK2-mediated HNF4α1 protein degradation enhanced Sox9 expression in colon cancer." (PMID 38659853, 2024). "DKK2 is required for the formation of LYZ+ colon cancer cells exhibiting Paneth cell properties such as glycolysis for stem cells." (PMID 38659853, 2024). "DKK2 expression in colon cancer promotes LYZ+ cancer cell generation through the regulation of HNF4α1, which suppresses expression of Sox9, the transcription factor for Paneth cell differentiation." (PMID 38659853, 2024). "Our findings suggest that DKK2 promotes LYZ+ cell formation exhibiting Paneth cell properties to develop cancer stem cell niches for outgrowth of metastasized colon cancers." (PMID 38659853, 2024). "Here we report that Dickkopf-2 (DKK2) is essential for the generation of cancer cells with Paneth cell properties during colon cancer metastasis." (PMID 38659853, 2024). "Cancer cells harboring Paneth cell properties were reduced in Dkk2 knockout metastasized colon cancer tissues in mice." (PMID 39535280, 2024). "- Overexpression of miR-766 contribute to inhibition of colon cancer development by decreasing methylation of tumor suppressor genes including DKK2, WIF1, SFRP1, and SFRP2." (PMID 37205191, 2023). "We demonstrated that the DKK2 blockade with the anti-DKK2 antibody 5F8 was effective in suppressing tumor progression using a syngeneic CRC model grafted with mouse colon cancer cell MC38 and a genetic benign CRC model using the ApcMin/+ mice." (PMID 32559853, 2020). "We found that the anti-DKK2 antibody 5F8 inhibited tumor progression in an advanced colon cancer model by modifying tumor immune microenvironment." (PMID 32559853, 2020). "HNF4A mediates the formation of Lysozyme positive colon cancer cells by DKK2." (PMID 38659853, 2024). "This suggests a reduction of LYZ+ cells in metastasized colon tumors by knockout a Dkk2 gene." (PMID 38659853, 2024). "DKK2-deficient colon cancer cells possessed high levels of HNF4α1 protein and failed to generate LYZ+ cancer cells in vitro and in vivo." (PMID 38659853, 2024).
colon cancer (continued). "In this study, we have shown that DKK2 promotes liver metastasis of colon cancer." (PMID 38659853, 2024). "This is consistent with our previous report that DKK2 enhances Lgr5 expression in colon cancer." (PMID 38659853, 2024). "Contrary to human homologues DKK1 and DKK2, whose silencing by CGI hypermethylation is indicated both in colon cancer cell lines and gastrointestinal tumors, Dkk1 downregulation in mice has been suggested to occur through factors independent of DNA hypermethylation." (PMID 24204690, 2013). "It was not determined if anti-DKK2 blockage could also gain the similar tumor inhibitory effect in advanced colon tumors." (PMID 32559853, 2020).
adenoma (5 papers, 2014 to 2025). A neoplasm arising from the epithelium. "Differential gene expression analysis of the scRNA-seq data from the adenoma cells showed substantially fewer transcripts encoding the Wnt antagonists Axin2, Dkk2, Dkk3, Wif1, Notum, and Nkd1 in the LApcL mice than in the LApc mice." (PMID 34788095, 2021). "For DKK2, nonspecific staining in the tumor duct was observed in nonadvanced adenoma; however, staining of the tumor adenoduct and stroma was observed in advanced adenoma." (PMID 38334454, 2024). "We discovered widespread hypermethylation of the Wnt antagonists SFRP1, SFRP2, SFRP5, DKK2, WIF1 and SOX17 in the transition from normal to adenoma with only the Wnt antagonists SFRP1, SFRP2, DKK2 and WIF1 showing further significant increase in methylation from adenoma to carcinoma." (PMID 25432628, 2014).
ovarian carcinoma (5 papers, 2015 to 2021). A malignant neoplasm originating from the surface ovarian epithelium. "it has been shown that Dkk2 is frequently methylated and therefore epigenetically silenced in ovarian cancer." (PMID 33679613, 2021). "Since its role in ovarian cancer has been conflicting so far this analysis focused on the correlation of Dkk2 with GPER to identify a possible link between Wnt and estrogen and investigating their potential prognostic significance." (PMID 33679613, 2021). "GPER has been proposed to act as tumor suppressor in ovarian cancer and to have, together with Wnt pathway modulator Dickkopf 2 (Dkk2) expression, a positive prognostic impact in ovarian cancer patients." (PMID 34831222, 2021). "In Kaplan-Meier analysis, subtype-specific evaluation did not reveal significant differences regarding OS between patients with high and low Dkk2 expression so that results can be considered as a base for further research in ovarian cancer." (PMID 33679613, 2021). "In this analysis, we investigated the expression of Dkk2 in the different histological subtypes of epithelial ovarian cancer, its relation to clinicopathological aspects and its impact on OS." (PMID 33679613, 2021). "Correlation between Dkk2 expression and clinicopathologic characteristics of ovarian cancer patients." (PMID 33679613, 2021). "But in melanoma, gastric cancer, renal cancer, and ovarian carcinoma, DKK2 expression is notably reduced." (PMID 31583260, 2019). "However, in combination with other factors like Luteinizing Hormone/Choriogonadotropin Receptor and Follicle Stimulating Hormone Receptor or Dkk2, it could serve as a positive prognostic factor for patients suffering from epithelial ovarian cancer." (PMID 33679613, 2021). "Dkk2 as a Wnt/β-catenin antagonist may play an important role in ovarian cancer." (PMID 33679613, 2021). "Also, they found that promoter hypermethylation of DKK2 might be a biomarker for ovarian cancer screening." (PMID 31583260, 2019). "For epithelial ovarian cancer (EOC), it has not been proven if either Dkk2 or the GPER on its own have an independent impact on overall survival (OS)." (PMID 33679613, 2021).
Ewing sarcoma (4 papers, 2016 to 2019). A small round cell tumor that lacks morphologic, immunohistochemical, and electron microscopic evidence of neuroectodermal differentiation. "Moreover, DKK2 played an important role in mediating osteolysis, invasiveness, and metastatic spread in Ewing sarcoma." (PMID 31583260, 2019). "Although no mutations in Wnt-related genes have been identified in Ewing sarcoma to date, a relationship between EWSR1-FLI1 and Wnt, as well as the involvement of DKK2 have been reported, which warrants further analysis." (PMID 31698687, 2019). "Indeed, several tumour-specific alterations seem to have multiple contradictory functions in a tumour, for example in Ewing Sarcoma the fusion protein EWS/ETS and other proteins overexpressed in this tumour, such as DKK2, contribute negatively to proliferation, but enhance metastasis." (PMID 29371599, 2018).
lymph node metastasis (4 papers, 2017 to 2022). "The correlation between DKK2 hypermethylation and the primary clinicopathological characteristics of cervical cancer, including histology, stage, lymph node metastasis, HPV infection, and differentiation, was investigated further." (PMID 37551167, 2022). "Intriguingly, we observed a correlation between high DKK2 expression and increased lymph node metastasis prevalence in these CRC patients as well." (PMID 32559853, 2020). "Intriguingly, we observed a correlation of high DKK2 expression with increased lymph node metastasis prevalence in these CRC patients as well." (PMID 32559853, 2020). "Patients with lymph node metastasis exhibited increased promoter methylation frequency (χ2 = 5.239, P = 0.022) and low DKK2 mRNA expression (χ2 = 3.958, P = 0.047) compared with patients with no lymph node metastasis." (PMID 37551167, 2022). "The methylation rate of the DKK2 promoter was 76.5% in cervical cancer specimens with lymph node metastasis, and only 45.2% in cervical cancer specimens without lymph node metastasis, indicating a significant difference between the 2 groups." (PMID 37551167, 2022). "Our data showed that the methylation status and expression of DKK2 were not correlated with the clinical features of breast tumor, such as pathological grade, ER status, and lymph node metastasis level." (PMID 28467796, 2017). "DKK2 methylation (76.5% vs 45.2%, respectively, χ2 = 5.239, P = 0.022) and DKK2 mRNA expression (11.8% vs 37.1%, respectively, χ2 = 3.958, P = 0.047) are significantly different between patients with or without lymph node metastasis." (PMID 37551167, 2022). "Also, we assessed the correlation between the DKK2 expression and the overall survival rate with patients grouped by clinic TNM stage classification, with or without lymph node metastasis and with or without vascular invasion." (PMID 31583260, 2019).
atherosclerosis (3 papers, 2017 to 2022). A disease characterized by the build-up of fatty material and calcium deposition in the arterial wall resulting in partial or complete occlusion of the arterial lumen. "Whether the rest of them, including Dkk2, Ltbp2, Lamb1, Cdca7l, Dclk1, and Slc45a4, are associated with atherosclerosis and d-flow has not been reported." (PMID 34282126, 2021).
colorectal tumors (3 papers, 2020 to 2025). "and 5-AVA further suppress the expression of DKK2, exacerbate obesity-related inflammation, and form a vicious cycle, thereby promoting the occurrence of colorectal tumors." (PMID 40340623, 2025). "In summary, 5-AVA may interact with KDM6B, regulate the Wnt/β-catenin signaling pathway by affecting the methylation of DKK2, and promote the development of colorectal tumors." (PMID 40340623, 2025). "Overall, the results suggest that Fusobacterium mortiferum and its metabolite 5-AVA may inhibit the expression of DKK2 through some mechanism, thereby activating the Wnt/β-catenin pathway and promoting the occurrence of colorectal tumors." (PMID 40340623, 2025).
esophageal adenocarcinoma (3 papers, 2019 to 2021). A malignant tumor with glandular differentiation arising predominantly from Barrett mucosa in the lower third of the esophagus. "A tissue micro array of 192 patients with esophageal adenocarcinoma was analyzed immunohistochemically for DKK2, miRNA-221 expression by RNA scope, and GATA6 amplification by fluorescence in-situ hybridization." (PMID 32075129, 2020). "One study focusing solely on esophageal adenocarcinomas showed that the chemoresistance was conveyed through alteration of the Wnt/β-catenin pathway and DKK2, CDH1, CD44, MYC, and ABCG2 expression." (PMID 31467538, 2019).
esophageal cancer (3 papers, 2020 to 2023). A primary or metastatic malignant neoplasm involving the esophagus. "Previous studies showed that DKK2 expression is modulated by expression of microRNA-221 (miRNA-221) in esophageal cancer." (PMID 36747258, 2023). "It was shown that DKK2 expression is modulated by expression of micro RNA-221 (miRNA-221) in esophageal cancer." (PMID 32075129, 2020). "So far, there is only limited data characterizing the role of DKK2 expression in esophageal cancer." (PMID 32075129, 2020). "Whether these mechanisms also apply in malignancies and in esophageal carcinoma in particular, as well as in DKK2, is unknown and needs further investigation." (PMID 32075129, 2020). "MiR-221 was overexpressed in 5-FU resistant esophageal cancer cells and EAC tissue and could potentiate 5-FU resistance by directly down-regulating the expression of dickkopf Wnt signaling pathway inhibitor 2 (DKK2) and activating the Wnt/β-catenin-EMT pathways." (PMID 34881242, 2021).
gastric cancer (3 papers, 2021 to 2023). A primary or metastatic malignant neoplasm involving the stomach. "In our study, the restoration experiments demonstrated circCNIH4 suppressed gastric cancer cell progression via elevating the expression of DKK2 and FRZB to repress Wnt/β-catenin pathway." (PMID 34364402, 2021). "Overexpression of DKK2 repressed the progression of gastric cancer cells through Wnt/β-catenin pathway." (PMID 34364402, 2021). "DKK2 is upregulated and predicates poor prognosis in pancreatic ductal adenocarcinoma, while in gastric cancer, DKK2 serves as a tumor-suppressor gene." (PMID 34364402, 2021). "This is the first study to elucidate the regulatory relationship between circCNIH4 and DKK2 or FRZB in gastric cancer; however, the precise molecular mechanism still needs to be further studied." (PMID 34364402, 2021). "However, the upregulation of lncRNA AWPPH was demonstrated to inhibit the proliferation and invasion of gastric cancer cells via the miR-203a/DKK2 axis in another study." (PMID 35794986, 2022). "Moreover, silencing of DKK2 or FRZB reversed circCNIH4 overexpression-mediated effects on gastric cancer cells." (PMID 34364402, 2021). "Finally, the in vivo experiment indicated that circCNIH4 inhibited tumor growth via DKK2 and FRZB in gastric cancer." (PMID 34364402, 2021). "CircCNIH4 induced the expression of DKK2 and FRZB in gastric cancer cells." (PMID 34364402, 2021). "Similar to DKK2, FRZB also plays an inhibitory role in Wnt/β-catenin pathway in gastric cancer." (PMID 34364402, 2021). "Additionally, circCNIH4 suppressed tumor growth via regulating DKK2 and FRZB expression in gastric cancer in vivo." (PMID 34364402, 2021). "Our study demonstrated that circCNIH4 played a tumor-inhibiting role through upregulating DKK2 and FRZB expression and suppressing Wnt/β-catenin pathway in gastric cancer, which might provide a potential biomarker for the diagnosis and treatment of gastric cancer." (PMID 34364402, 2021). "However, the regulatory mechanism between circHECTD1 and DKK2 or FRZB has not been elucidated in gastric cancer." (PMID 34364402, 2021). "Then, we found Wnt antagonist genes DKK2 and FRZB were upregulated by circCNIH4 overexpression in MKN-74 and HGC-27 cells and proved that circCNIH4 played its function by regulating DKK2 and FRZB expression and inactivating Wnt/β-catenin pathway in gastric cancer cells." (PMID 34364402, 2021).